TRBV3-1 (T cell receptor beta variable 3-1)
Description:
V region of the variable domain of T cell receptor (TR) beta chain that participates in the antigen recognition. Alpha-beta T cell receptors are antigen specific receptors which are essential to the immune response and are present on the cell surface of T lymphocytes. Recognize peptide-major histocompatibility (MH) (pMH) complexes that are displayed by antigen presenting cells (APC), a prerequisite for efficient T cell adaptive immunity against pathogens. Binding of alpha-beta TR to pMH complex initiates TR-CD3 clustering on the cell surface and intracellular activation of LCK that phosphorylates the ITAM motifs of CD3G, CD3D, CD3E and CD247 enabling the recruitment of ZAP70. In turn ZAP70 phosphorylates LAT, which recruits numerous signaling molecules to form the LAT signalosome. The LAT signalosome propagates signal branching to three major signaling pathways, the calcium, the mitogen-activated protein kinase (MAPK) kinase and the nuclear factor NF-kappa-B (NF-kB) pathways, leading to the mobilization of transcription factors that are critical for gene expression and essential for T cell growth and differentiation. The T cell repertoire is generated in the thymus, by V-(D)-J rearrangement. This repertoire is then shaped by intrathymic selection events to generate a peripheral T cell pool of self-MH restricted, non-autoaggressive T cells. Post-thymic interaction of alpha-beta TR with the pMH complexes shapes TR structural and functional avidity.
Synonyms: TCRBV9S1A1T; TRBV31; TCRBV3S1
Tractability: Antibody: UniProt places it where antibodies can reach, with medium confidence; UniProt predicts a signal peptide or a membrane-spanning region; its Gene Ontology location is reachable by antibodies, with medium confidence.
Gene: T-cell receptor variable (V) gene on chromosome 7 (142,308,542 to 142,309,048, forward strand). Ensembl gene ENSG00000237702.
Subcellular location: Cell membrane
Gene Ontology:
Biological process: cell surface receptor signaling pathway
Cellular component: plasma membrane
Homologues: Orthologues: rabbit TRBV3-1 (77% identical), mouse Trbv4 (68% identical), pig TRBV3-1 (61% identical), rat Trbv4 (61% identical). Paralogues in human: TRBV4-1 (61% identical), TRBV4-2 (61% identical), TRBV9 (46% identical), TRBV12-5 (41% identical), TRBV18 (41% identical), TRBV23-1 (41% identical), TRBV12-4 (40% identical), TRBV5-1 (39% identical), TRBV13 (39% identical), TRBV2 (39% identical), TRBV5-5 (39% identical), TRBV11-3 (38% identical), and 39 more.
Diseases named in the same sentence as TRBV3-1 in open-access papers:
TRBV3-1 is named in the same sentence as 8 diseases in open-access papers, as found by Europe PMC text mining. Sharing a sentence is not in itself a finding about the gene and the disease. The quoted sentences say what the papers report.
atherosclerosis (1 paper, 2025). A disease characterized by the build-up of fatty material and calcium deposition in the arterial wall resulting in partial or complete occlusion of the arterial lumen. "Additionally, Trbv1 was associated with reactive arthritis [S23] and myeloperoxidase‐induced autoimmunity [S24], and Trbv31 was linked to atherosclerosis [S25]." (PMID 40665793, 2025).
COVID-19 (1 paper, 2024). A disease caused by infection with severe acute respiratory syndrome coronavirus 2. "The expression of genes such as TRDV2, TRVD1, TRAV38-1, TRBV3-1, TRAV13-1, and TRBV2 was among the 15 most decreased in all data of severe COVID-19." (PMID 38262689, 2024).
viral infection (1 paper, 2020). "Quantifying the percent of unique clones aligning to each V-gene revealed a substantial (>40% of unique clones) portion of the unsorted blood repertoire consisted of TRBV1 and TRBV31 before viral infection." (PMID 32547546, 2020).
bacterial infection (1 paper, 2023). "PRP also upregulated the genes involved in the beta chain of the T cell receptor (TRBV3‐1, TRBV6‐5, TRBV7‐2, TRBV27, TRBC2, and TRBJ2‐3), which is responsible for antigen recognition and activation of cellular immunity during bacterial infection." (PMID 36704119, 2023).
tumor (1 paper, 2022). "One possible explanation for the potential diagnostic biomarker of the TRBV3-1 gene is that the mature T cells containing this gene may be activated and expanded by tumor-associated antigens." (PMID 35967453, 2022). "In our study, the TRBV3-1 gene was enriched in the tumor group." (PMID 35967453, 2022).
TRBV3-1 also shares sentences with these, for which no sentence is quoted: autoimmune disease (1 paper); Autoimmunity (1); reactive arthritis (1).